SLAMF7 (SLAM family member 7)
Diseases named in the same sentence as SLAMF7 in open-access papers (continued):
Sharing a sentence is not in itself a finding about the gene and the disease.
CMV infection (2 papers, 2021 to 2025). "Moreover, we found that prior CMV infection was associated with a higher relative gene expression of SLAMF7 and NKG7." (PMID 35087511, 2021). "Principal component analysis of the five SLAMF7 and NKG7 splice variants, which expression was influenced by prior CMV infection, revealed two components." (PMID 35087511, 2021). "In addition, expression levels of SLAMF7 and NKG7 were affected by prior cytomegalovirus infection in LTx recipients." (PMID 35087511, 2021).
colorectal cancer (2 papers, 2022 to 2025). A primary or metastatic malignant neoplasm that affects the colon or rectum. "Furthermore, when cocultured with the SLAMF7− human colorectal cancer cell line Colo205, SLAMF7+ hDNT induced significantly higher levels of tumor cell apoptosis and more effectively killed tumor cells than SLAMF7− hDNT." (PMID 41168829, 2025). "In addition, a recent study found that SLAMF7 can mediate ICD in colorectal cancer cells." (PMID 36425071, 2022).
gastric cancer (2 papers, 2022 to 2024). A primary or metastatic malignant neoplasm involving the stomach. "In agreement with our results in primary gastric cancers, KLF2pos xenografts had high expression of plasma cell markers IRF4 and SLAMF7 in the humanized mice only, reflecting increased plasma cell recruitment associated with KLF2." (PMID 34642171, 2022).
glioma (2 papers, 2024). A benign or malignant brain and spinal cord tumor that arises from glial cells (astrocytes, oligodendrocytes, ependymal cells). "The strategy facilitates the uptake of tumor cells by SLAMF7‐expressing macrophages and activates innate and cellular immunity in glioma, thereby effectively controlling the progression of the disease." (PMID 39713206, 2024). "However, the expression levels of IL‐12, CD47, and SLAMF7 were higher in tumors than in adjacent non‐tumorous tissues, as determined by analyzing their mRNA expression levels in glioma patients using TCGA and GTEx datasets." (PMID 39713206, 2024). "Immunofluorescence analysis of tumor sections and non‐tumor sections showed that SLAMF7 was mainly localized to the tumor periphery, with lower levels in the tumor core, implying that SLAMF7 expression may hinder glioma development." (PMID 39713206, 2024).
head and neck squamous cell carcinoma (2 papers, 2025). A squamous cell carcinoma that arises from any of the following anatomic sites: lip and oral cavity, nasal cavity, paranasal sinuses, pharynx, larynx, and salivary glands. "SLAMF7 expression was significantly elevated in tumor tissues from multiple cancers, including head and neck squamous cell carcinoma (HNSC), kidney renal clear cell carcinoma (KIRC), kidney renal papillary cell carcinoma (KIRP), and lung adenocarcinoma (LUAD)." (PMID 41168829, 2025).
Hepatitis (2 papers, 2013 to 2023). Inflammation of the liver. "Moreover, recent studies also reported the role of SLAMF7 in HIV infection and poly I:C/d-galactosamine–induced hepatitis." (PMID 36749634, 2023).
mantle cell lymphoma (2 papers, 2019 to 2024). Mantle cell lymphoma is a rare form of malignant non-Hodgkin lymphoma affecting B lymphocytes in the lymph nodes in a region called the ``mantle zone''. "Importantly, surface expression of SLAMF7 was also not detected on primary patient-derived DLBCL or mantle cell lymphoma (MCL) cells." (PMID 30710089, 2019).
neuroblastoma (2 papers, 2022 to 2024). Neuroblastoma (NB) is the most common solid, extracranial childhood tumor. "The immunohistochemistry analysis revealed that SLAMF7 expression was detected on macrophages and a restricted number of high-risk neuroblastoma cells." (PMID 38920727, 2024). "Because homotypic interaction is a mode of action of SLAMF7, the expression of SLAMF7 on both macrophages and some high-risk neuroblastoma cells supports the idea that SLAMF7 is a potential therapeutic target for killing the tumor cells." (PMID 38920727, 2024). "We have also explored clinical relevance of the SLAMF7 pathway in the anti-high-risk neuroblastoma immune response." (PMID 35525858, 2022). "Nonetheless, our preliminary analysis indicates that other SLAM family genes are expressed at compatible levels to that of SLAMF7 in high-risk neuroblastoma tissues (SLAMF2, SLAMF5, and SLAMF8)." (PMID 35525858, 2022). "A combination of PD-1 blockade and anti-SLAMF7 could therefore maximize the effector function of macrophages in a subpopulation of high-risk neuroblastomas (Group 1)." (PMID 35525858, 2022). "We have become interested in a potential involvement of the SLAMF7 pathway in tumor phagocytosis of macrophages in high-risk neuroblastoma because biological effect of the SLAMF7 pathway on the clinical behavior of neuroblastoma has not been addressed previously." (PMID 35525858, 2022). "Our data suggest that the majority of high-risk neuroblastomas could express SLAMF7." (PMID 35525858, 2022). "Thus, the use of anti-SLAMF7 antibody as therapeutics for high-risk neuroblastoma could enhance effector functions of both CD4 CTL and macrophages." (PMID 35525858, 2022). "High-level co-expression of SLAMF7 and SH2D1B was significantly associated with better survival of the high-risk neuroblastoma patients." (PMID 35525858, 2022). "We have reported CD4 CTL as an important effector of high-risk neuroblastoma, and work by others on adult cancers has indicated that cytotoxic activity of tumor-specific cytolytic CD4 T cells is in part dependent on SLAMF7." (PMID 35525858, 2022). "In this study, we performed gene expression profiling and survival analyses on large neuroblastoma datasets to address the prognostic effect of PD-L1 gene expression and the possible involvement of the SLAMF7 pathway in the anti-neuroblastoma immunity." (PMID 35525858, 2022). "Our results show that high-level co-expression of SLAMF7 and SH2D1B is significantly associated with better outcome of high-risk neuroblastoma patients." (PMID 35525858, 2022). "Furthermore, high-level co-expression of SLAMF7 and CD68 was significantly associated with better outcome of high-risk neuroblastoma patients." (PMID 35525858, 2022). "Moreover, high-level co-expression of SLAMF7 and SH2D1B was significantly associated with better survival of high-risk neuroblastoma patients." (PMID 35525858, 2022). "We next addressed if the trans-interaction between SLAMF7 on macrophages and neuroblastoma cells could occur by examining SLAMF7 expression on the tumor cells relative to those of B4GALNT1 (GD2 synthase gene) and ST8SIA1 (GD3 synthase gene) in high-risk neuroblastoma tissues." (PMID 35525858, 2022).
renal cell carcinoma (2 papers, 2022 to 2025). "Of particular interest, SLAMF7 has recently been shown to program T cells toward exhaustion phenotype via SLAMF7+ tumor-associated macrophages (TAMs) in the tumor microenvironment of renal cell carcinoma." (PMID 36142814, 2022). "For example, in renal cell carcinoma, activation of the self-ligand SLAMF7 immune receptor on T cells induces STAT1 and STAT3 phosphorylation and the expression of multiple inhibitory receptors and transcription factors associated with T-cell exhaustion." (PMID 40646691, 2025).
abscess (1 paper, 2025). An inflammatory process characterized by the accumulation of pus within a newly formed tissue cavity which is the result of a bacterial, fungal, or parasitic infection or the presence of a foreign body. "AKRB10 and SLAMF7 were positively correlated with abscess count (r = 0.56, p = 0.03; r = 0.59, p = 0.02)." (PMID 40455785, 2025).
brain tumors (1 paper, 2024). "Results indicated that SLAMF7 was primarily expressed in macrophages of brain tumors, suggesting that the nCD47‐SLAMF7 fusion protein may principally act on macrophages to promote tumor cell uptake." (PMID 39713206, 2024).
brucellosis (1 paper, 2025). Brucellosis is a bacterial infection that spreads from animals to people via unpasteurized dairy products or by exposure to contaminated animal products or infected animals. "Here, human blood transcriptomic analyses reveal the involvement of SLAMF7 and SLAMF8 in many infectious diseases, with elevated levels associated with type I IFN responses in salmonellosis and brucellosis patients." (PMID 40231463, 2025). "Future studies should reveal whether the SLAMF7/8-elicited type I IFN production by pDCs plays a role in the maintenance of immune homeostasis via metabolic reprogramming in brucellosis or salmonellosis, as globally reported for type I IFN during chronic viral infection." (PMID 40231463, 2025). "Here, we reveal the participation of SLAMF7 (CS1, CRACC, CD319) and SLAMF8 (BLAME, CD353) in a broad spectrum of infectious diseases, showing increased levels in the blood of salmonellosis and brucellosis patients that correlate with a type I IFN response." (PMID 40231463, 2025). "Altogether these data identify SLAMF7 and SLAMF8 as hallmarks of acute brucellosis and link their overexpression to type I IFN responses." (PMID 40231463, 2025). "To determine whether SLAMF7 and SLAMF8 expression may vary in human pDCs during brucellosis, we infected CAL-1 cells with B. abortus or B. melitensis, the 2 main pathogenic species causing infection in humans." (PMID 40231463, 2025). "Several genes of the SLAM family (SLAMF1, SLAMF7, and SLAMF8) were overexpressed in acute but not in chronic brucellosis patients, unlike stable TLR9 gene expression." (PMID 40231463, 2025).
Burkitt lymphoma (1 paper, 2024). A rare form of malignant mature B-cell non-Hodgkin lymphoma. "SLAMF7/CD319 was also found to be positive in Raji (80–100% positive cells) and partially positive in Daudi (40–60%), Namalwa (60–80%), and Ramos (60–80%) Burkitt lymphoma B cell lines." (PMID 38612827, 2024).
clear cell renal cell carcinoma (1 paper, 2025). "In clear cell renal cell carcinoma, elevated SLAMF7 expression was associated with poor prognosis and a macrophage-dominant immune phenotype, indicating its potential as a therapeutic target to restore antitumor immunity." (PMID 41009979, 2025).
colitis (1 paper, 2025). Inflammation of the colon. "Given that SLAMF7-deficient mice exhibited dramatically reduced susceptibility to colitis compared with WT mice and that SLAMF7 activated by recombinant SLAMF7 exacerbates colitis, we expect that blockade of SLAMF7 would relieve intestinal inflammation and have important therapeutic implications." (PMID 40646691, 2025). "Subsequently, these mice were exposed to DSS, and it was observed that SLAMF7 silencing ameliorated DSS-induced colitis, as evidenced by reduced weight loss, increased colon length, a lower DAI score, and an increased number of goblet cells compared to those of WT-siNC mice." (PMID 40646691, 2025). "We found that the expression of SLAMF7 was significantly greater in patients with colitis than in healthy donors." (PMID 40646691, 2025). "Using DSS-induced colitis in an acute colon tissue inflammation model, we also observed increased SLAMF7 expression during inflammation, suggesting a potential link between SLAMF7 and intestinal inflammation." (PMID 40646691, 2025). "To determine whether SLAMF7 is clinically relevant to intestinal inflammation in humans, we assessed SLAMF7 expression in colon tissue by using publicly available human gene expression data, which included data from ten healthy donors and ten colitis patients." (PMID 40646691, 2025). "Compared with that in WT mice, DSS-induced colitis was markedly reduced in mice without SLAMF7." (PMID 40646691, 2025).
colorectal tumor (1 paper, 2025). "Furthermore, we transfected plasmids to SLAMF7 non-expressing CT26 colorectal tumor cells to upregulate their SLAMF7 expression." (PMID 41168829, 2025).
diarrheal disease (1 paper, 2025). The condition of having at least three loose or liquid bowel movements each day. "A second cohort of patients, comprising children under 10 years of age afflicted with diarrheal diseases, confirmed a significant upregulation of SLAMF7 and SLAMF8 in those diagnosed with Salmonella gastroenteritis." (PMID 40231463, 2025).
experimental autoimmune encephalomyelitis (1 paper, 2022). An autoimmune demyelinating disease of the central nervous system that is produced experimentally in animals by the injection of homogenized brain or spinal cord in Freund's adjuvant. "To define the role of SLAMF7 in CNS inflammation and MS pathogenesis, we used the murine model of MS, experimental autoimmune encephalomyelitis (EAE), and found SLAMF7−/− mice to be more susceptible to CNS autoimmunity compared to their WT counterparts." (PMID 36199066, 2022).
graft versus host disease (1 paper, 2024). An immune system disorder that occurs after allogeneic hematopoietic stem cell transplant and is a reaction of donor immune cells against host tissues. "These modifications aim to minimize the potential risk for allo-TCR-mediated graft-versus-host disease (GvHD) and to prevent SLAMF7-mediated fratricide." (PMID 39060023, 2024).
hepatocellular carcinoma (1 paper, 2025). A malignant tumor that arises from hepatocytes. "Consistently, a very recent study revealed that in hepatocellular carcinoma (HCC), SLAMF7 upregulation was observed in immunotherapy-responsive HCC tumors, with responding patients exhibiting elevated serum SLAMF7 levels." (PMID 40646691, 2025).
intestinal inflammation (1 paper, 2025). "Consistently, SLAMF7 activation impaired intestinal barrier integrity and increased susceptibility to gut inflammation, whereas SLAMF7 knockdown with siRNA alleviated DSS-induced intestinal inflammation." (PMID 40646691, 2025). "SLAMF7 deficiency altered the gut microbiome, specifically promoting mucus-specific bacteria such as Akkermansia muciniphila, and protected against DSS-induced intestinal inflammation." (PMID 40646691, 2025).
leprosy (1 paper, 2021). Leprosy is a chronic infectious disease affecting primarily the skin and peripheral nervous system. "As for differentiating leprosy per se vs. ODD, genes IDO1, BLK (exon 11), CD38, CXCL11, and SLAMF7, all had an area under the curve (AUC) of at least 96% with their lower bound 97% confidence intervals above 90%." (PMID 34695167, 2021). "Indoleamine 2,3-dioxygenase 1 (IDO1) expression alone was highly discriminatory, followed by TLR10, BLK, CD38, and SLAMF7, whereas the HS3ST2 and CD40LG mRNA separated multi- and paucibacillary leprosy." (PMID 34695167, 2021).
lung carcinoma (1 paper, 2021). "Nor did we find that cg00045592 in SLAMF7 was causally associated with lung cancer risk." (PMID 33729499, 2021).
lupus erythematosus (1 paper, 2012). An autoimmune, connective tissue chronic inflammatory disorder affecting the skin, joints, kidneys, lungs, heart, and the peripheral blood cells. "More recently, a reduced expression on monocytes and NK cells with a simultaneous increase of SLAMF7 on B cells was observed in patients with lupus erythematosus." (PMID 23029029, 2012).
metastatic melanoma (1 paper, 2025). A melanoma that has spread from its primary site to another anatomic site. "It showed high accuracy in predicting metastatic melanoma immunotherapy response and identified a critical T cell subcluster expressing FCRL3 and SLAMF7." (PMID 41309494, 2025).
myocardial infarction (1 paper, 2024). Gross necrosis of the myocardium, as a result of interruption of the blood supply to the area, as in coronary thrombosis. "Five proteins deregulated in homozygous LAV-BPIFB4 carriers (e.g. CXCL11, CSF-1, SLAMF7, IL-10RB and TNFRSF9) emerged from a recent proteome-based CV risk model as the top factors predicting myocardial infarction event." (PMID 38468336, 2024).
neutropenia (1 paper, 2021). A decrease in the number of neutrophils found in the blood. "The MAbs targeting SLAMF7 group had a lower risk of neutropenia than the MAbs targeting PD-1/ PD-L1 and CD38 groups." (PMID 34488679, 2021).
Salmonella Infections (1 paper, 2025). Infections with bacteria of the genus SALMONELLA. "SLAMF7 and SLAMF8 signal through NF-κB, IRF7, and STAT-1, and limit mitochondrial ROS accumulation upon Salmonella infection." (PMID 40231463, 2025). "To analyze the role of SLAMF7 and SLAMF8 in human primary pDCs, we next examined the effect of the direct engagement of one of these two receptors by a specific antibody or its isotype control on the response of these cells to Salmonella infection." (PMID 40231463, 2025). "Indeed, prokaryotic RNA purified from E. coli or S. Typhimurium increased the percentage of SLAMF7+ and SLAMF8+ CAL-1 cells in an RNase-dependent manner, as well as the surface levels of SLAMF7 and SLAMF8, in primary human pDCs, like in the case of Salmonella infection." (PMID 40231463, 2025). "Finally, we examined whether the higher levels of mtROS found in the absence of SLAMF7 or SLAMF8 influence the intracellular signaling initiated in pDCs by Salmonella infection." (PMID 40231463, 2025).
sarcoidosis (1 paper, 2020). Sarcoidosis is a multisystemic disorder of unknown cause characterized by the formation of immune granulomas in involved organs. "Only three DEGs, SLAMF7, DC27, and CXCL13, were dysregulated in all three diseases (sarcoidosis, TB, CM)." (PMID 33276795, 2020).
skin cancer (1 paper, 2017). "We found multiple UV target genes to be critical to the survival of skin cancer cells, including CD200, GJA5, GPR115, KLK7, SLAMF7 and SLP1." (PMID 28211524, 2017). "Our analysis also identified several new UV target genes, including CYP24A1, GJA5, SLAMF7 and ETV1, which were frequently dysregulated in human squamous cell carcinomas, highlighting their potential as new molecular targets for prevention or treatment of UVR-induced skin cancers." (PMID 28211524, 2017).
systemic AL amyloidosis (1 paper, 2016). "Furthermore, alemtuzumab, an anti‐CD52 antibody 28, or elotuzumab, a humanized monoclonal antibody against the surface antigen SLAMF7 29, may offer new treatment options in systemic AL amyloidosis for positive patients." (PMID 27109862, 2016).
X-linked lymphoproliferative disease (1 paper, 2018). X-linked lymphoproliferative disease is a hereditary immunodeficiency characterized, in the majority of cases, by an inadequate immune response to infection with the Epstein-Barr virus (EBV). "In addition, antibody engagement of SLAMF7 stimulated comparable levels of cytotoxicity by NK cells from both SAP-deficient X-linked lymphoproliferative disease patients and healthy donors, further indicating that SLAMF7 activation signaling is independent of SAP." (PMID 30455698, 2018).